SLC35A2 (solute carrier family 35 member A2)
Description:
Transports uridine diphosphate galactose (UDP-galactose) from the cytosol into the Golgi apparatus, functioning as an antiporter that exchanges UDP-galactose for UMP. It is also able to exchange UDP-galactose for AMP and CMP, and to transport UDP-N-acetylgalactosamine (UDP-GalNAc) and other nucleotide sugars. As a provider of UDP-galactose to galactosyltransferases present in the Golgi apparatus, it is necessary for globotriaosylceramide/globoside (Gb3Cer) synthesis from lactosylceramide.
Synonyms: UDP-Gal-Tr; UGT; UGALT; UGTL; UGAT; UGT1; UGT2; CDG2M; CDGX
Tractability: Antibody: UniProt predicts a signal peptide or a membrane-spanning region. PROTAC: its protein half-life has been measured.
Target class: Electrochemical transporter; SLC35 family of nucleotide sugar transporters; Transporter; SLC superfamily of solute carriers
Gene: Protein-coding gene on chromosome X (48,903,180 to 48,911,958, reverse strand). Ensembl gene ENSG00000102100.
Subcellular location: Endoplasmic reticulum membrane (Isoform 1); Golgi apparatus membrane; Golgi apparatus membrane (Isoform 2)
Subcellular location (Human Protein Atlas): Golgi apparatus
Pathways (Reactome):
Disease: Defective SLC35A2 causes congenital disorder of glycosylation 2M (CDG2M)
Transport of small molecules: Transport of nucleotide sugars
Gene Ontology:
Molecular function: protein binding; UDP-galactose transmembrane transporter activity; pyrimidine nucleotide-sugar transmembrane transporter activity
Biological process: UDP-galactose transmembrane transport; galactose metabolic process; nucleobase-containing compound transport; organophosphate ester transport; pyrimidine nucleotide-sugar transmembrane transport
Cellular component: endoplasmic reticulum; endoplasmic reticulum membrane; Golgi apparatus; Golgi membrane; membrane
Gene-disease validity (ClinGen):
ClinGen rates the evidence that SLC35A2 causes each of these diseases.
X-linked complex neurodevelopmental disorder (X-linked): Definitive. A complex neurodevelopmental disorder that is transmitted via X-linked inheritance, and is characterized by intellectual disability, autism and epilepsy.
Homologues: Orthologues: macaque SLC35A2 (99% identical), rabbit SLC35A2 (97% identical), pig SLC35A2 (97% identical), guinea pig SLC35A2 (96% identical), mouse Slc35a2 (96% identical), dog SLC35A2 (95% identical), rat Slc35a2 (95% identical), chimpanzee SLC35A2 (86% identical), tropical clawed frog SLC35A2 (68% identical), zebrafish slc35a2 (62% identical), Drosophila melanogaster Ugalt (44% identical). Paralogues in human: SLC35A3 (43% identical), SLC35A1 (37% identical), SLC35A5 (22% identical), SLC35A4 (22% identical).
Diseases named in the same sentence as SLC35A2 in open-access papers:
SLC35A2 is named in the same sentence as 109 diseases in open-access papers, as found by Europe PMC text mining. Sharing a sentence is not in itself a finding about the gene and the disease. The quoted sentences say what the papers report.
epilepsy (19 papers, 2019 to 2026). A brain disorder characterized by episodes of abnormally increased neuronal discharge resulting in transient episodes of sensory or motor neurological dysfunction, or psychic dysfunction. "On the other hand, exome sequencing of brain specimens from 56 individuals with drug‐resistant epilepsy identified five patients with somatic de novo SLC35A2 gene variants." (PMID 41554664, 2026). "Since then, somatic SLC35A2 variants have been increasingly identified in drug‐resistant focal epilepsy, early epileptic encephalopathy, and epilepsy with mild malformations of cortical development with oligodendroglial hyperplasia (MOGHE)." (PMID 41554664, 2026). "MOGHE is a distinct entity of drug-resistant epilepsy associated with SLC35A2 variants, characterized by age-dependent phenotypes." (PMID 39902276, 2025). "In patients with MOGHE (mild cortical dysplasia with oligodendrogliosis and epilepsy), somatic mutations in the SLC35A2 gene result in loss of UDP-galactose transporter function." (PMID 41409784, 2025). "Genetically, lesion-confined mTOR-pathway mosaicism accounts for a substantial subset of FCD type II, while SLC35A2 mutations underlie mild malformation of cortical development with oligodendroglial hyperplasia in epilepsy (MOGHE)." (PMID 41155206, 2025). "All nine children with somatic SLC35A2 variants in brain were reclassified to mild malformation of cortical development with oligodendroglial hyperplasia in epilepsy." (PMID 39926610, 2025). "In humans, somatic variants of SLC35A2 are associated with mild malformation of cortical development with oligodendroglial hyperplasia in epilepsy (MOGHE)." (PMID 41008563, 2025). "Common symptoms related to SLC35A2 variants include epilepsy, psychomotor developmental delay, hypotonia, abnormal facial and skeletal features, and various magnetic resonance imaging (MRI) findings." (PMID 31231989, 2019). "In addition, SLC35A2, which encodes the UDP-galactose transporter involved in glycosylation, also plays a role in the pathogenesis of epilepsy." (PMID 41409784, 2025). "However, it is noteworthy that individuals carrying SLC35A2 nonsense variants experienced an earlier onset of epilepsy at an average age of 2.3 years, compared to 4.9 years for those with missense variants." (PMID 40042641, 2025). "Furthermore, recent studies have linked brain somatic variations in SLC35A2 to mild malformation of cortical development with oligo dendroglial hyperplasia in epilepsy." (PMID 41437099, 2025). "In line with the observed genotype-phenotype association, cumulating evidence suggests the pathogenicity of SLC35A2 in the development of epilepsy." (PMID 39902276, 2025). "SLC35A2‐CDG is an important disorder in the management of epilepsy." (PMID 40191061, 2025). "Experimental studies with SLC35A2 knockdown or knockout may shed further light on its role in neuronal migration, myelin formation, and the development of epilepsy." (PMID 39902276, 2025). "Despite these cytoarchitectural abnormalities, no spontaneous seizures were detected in these mouse models, suggesting that focal Slc35a2 deficiency primarily induces structural and microcircuit-level alterations without progressing to overt epilepsy." (PMID 41373710, 2025). "These range from systemic conditions such as congenital disorders of glycosylation (SLC35A2-CDG) to focal cortical malformations, most notably mild malformation of cortical development with oligodendroglial hyperplasia in epilepsy (MOGHE)." (PMID 41373710, 2025). "Patients affected with SLC35A2-CDG display hypogalactosylation of N-glycans and severe neurological symptoms such as epilepsy, intellectual disability, cerebral atrophy, and hypotonia." (PMID 41008563, 2025). "However, a distantly similar male case of SLC35A2-CDG without epilepsy, with only minor neurological involvement and with growth deficiency, has been described recently." (PMID 36831116, 2023).
breast carcinoma (10 papers, 2021 to 2025). "The study also assesed the association between SLC35A2 expression and breast cancer clinicopathological features of breast cancer, as well as its impact on overall survival." (PMID 38639872, 2024). "Recent research revealed the E2F-targeted pathway is associated with high SLC35A2 expression in breast cancer." (PMID 37569304, 2023). "SLC35A2 is associated with hypoxia-inducible factors, heat shock proteins, transcription factors, and DNA damage-associated signaling and is involved in the regulation of neutrophil and macrophage polarization in breast cancer." (PMID 36267313, 2022). "Pertaining to cancer, a previous report identified that high expression of SLC35A2 is corresponded with worse recurrence-free survival in patients with breast cancer." (PMID 40303483, 2025). "Survival analysis indicated that patients with low SLC35A2 expression had a more favorable prognosis in HER2-positive subtype breast cancer (P = 0.017)." (PMID 38639872, 2024). "Kaplan Meier survival curve suggested that HER2 positive subtype breast cancer patients have poor prognosis with high SLC35A2 expression." (PMID 38639872, 2024). "The role of SLC35A2 in breast cancer remains poorly understood, with limited available information on its significance." (PMID 38639872, 2024). "Although this study had some limitations, the relationship between the expression of SLC35A2 and clinicopathological parameters and prognosis of breast cancer has been verified." (PMID 38639872, 2024). "In order to have a better understanding of SLC35A2 in breast cancer, we investigated its expression profile, clinical significance and the impact of its expression on survival." (PMID 38639872, 2024). "In comparison to adjacent non-neoplastic tissues, a significantly higher expression of SLC35A2 was observed in breast cancer tissues (P = 0.020), and this expression was found to be independently correlated with HER2 positivity (P = 0.001)." (PMID 38639872, 2024). "Based on the information from TCGA database, SLC35A2 expression positively correlates with SLC3A2 expression in human breast cancer." (PMID 38639872, 2024). "This study aimed to investigate the expression of SLC35A2 and clinicopathological variables in breast cancer patients." (PMID 38639872, 2024). "This study aims to explore the relationship between SLC35A2 expression and clinical parameters of breast cancer, and the influence of SLC35A2 expression on the prognosis of breast cancer patients." (PMID 38639872, 2024). "It was concluded that patients with low SLC35A2 expression had a better prognosis for HER2-positive subtype breast cancer by survival analysis (P = 0.017)." (PMID 38639872, 2024). "Their study lacked detailed analysis for breast cancer, such as the relationship between different clinical characteristics of breast cancer patients and SLC35A2, which is complementary to our study." (PMID 38639872, 2024). "SLC35A2 can be used as an independent prognostic indicator of breast cancer patients and a possible biomarker in immunotherapy." (PMID 37889544, 2023). "In hormone receptor-positive subtypes of breast cancer (viz., ER+, PR+, and HER+), the SLC35A2 expression level was likewise associated with poorer prognostic features and poor survival." (PMID 34944621, 2021). "Our findings demonstrated that SLC35A2 overexpression should be further evaluated as a indicator for poor prognosis and possible biomarker for breast cancer stratification." (PMID 34944621, 2021). "In breast cancer, a few studies have slightly explored the possible mechanism of SLC35A2." (PMID 40303483, 2025). "Anti-SLC35A2 therapy maybe an option to overcome resistance to HER2 blockade for HER2 positive subtype breast cancer patients." (PMID 38639872, 2024). "Although evidence has shown that SLC35A2 may play a role in tumorigenesis, its expression and clinicopathological significance in breast cancer are still unclear." (PMID 38639872, 2024).
breast carcinoma (continued). "Furthermore, breast cancer patients with the HER2 positive subtype who exhibited decreased levels of SLC35A2 expression demonstrated improved long-term prognostic outcomes." (PMID 38639872, 2024). "We obtained the gene expression and protein levels of SLC35A2 in a variety of tumors from Molecular Taxonomy of Breast Cancer International Consortium, The Cancer Genome Atlas, Gene Expression Omnibus, Chinese Glioma Genome Atlas, and Human Protein Atlas databases." (PMID 37275857, 2023). "Moreover, expression of SLC35A2 may serve as a novel prognostic marker for HER2 positive subtype breast cancer." (PMID 38639872, 2024). "The primary limitation of this work is the retrospective nature of the transcriptome analysis, that may require additional validation in larger scale studies to evaluate the feasibility of SLC35A2 expression as novel biomarker in diagnosis and treament of female breast cancer." (PMID 34944621, 2021). "When all subtypes of breast cancer were analyzed together, SLC35A2 expression was not related to OS (P = 0.120)." (PMID 38639872, 2024). "Breast cancer tissues were statistically significantly more likely to express SLC35A2 than adjacent noncancerous tissues (P = 0.020)." (PMID 38639872, 2024). "Immunohistochemical analysis of SLC35A2 protein was conductedon 40 adjacent non-neoplastic tissues and 320 breast cancer tissues." (PMID 38639872, 2024). "Compared with adjacent non-neoplastic tissues, high SLC35A2 expression were observed in breast cancer tissues significantly (P = 0.020)." (PMID 38639872, 2024). "Our findings demonstrated that SLC35A2 was highly expressed in breast cancer tissues compared with adjacent non-neoplastic tissues." (PMID 38639872, 2024). "SLC35A2 may contribute to the growth of tumor, but particular functions of SLC35A2 in breast cancer are still unclear regardless of awareness that they play critical roles in tumorigenesis and progression." (PMID 38639872, 2024).
congenital disorder of glycosylation (6 papers, 2021 to 2025). Congenital disorder of glycosylation (CDG) is a fast growing group of inborn errors of metabolism characterized by defective activity of enzymes that participate in glycosylation (modification of proteins and other macromolecules by adding and processing of oligosaccharide side chains). "Mutations in the SLC35A2 gene located on chromosome X induce congenital glycosylation disorders." (PMID 35847988, 2022). "Studies have demonstrated a close relation of the pathogenic variation of SLC35A2 gene to a congenital disorder of glycosylation (CDG), resulting in metabolic disorders of glycan biosynthesis or assembly." (PMID 37467193, 2023). "SLC35A2 is an X-linked gene that encodes the Golgi-localized UDP-galactose transporter; variants of this gene can cause a congenital glycosylation disorder." (PMID 36119689, 2022).
epileptic encephalopathies (6 papers, 2021 to 2025). "In addition, male patients with mosaic SLC35A2 variants were reported to exhibit more severe symptoms, including epileptic encephalopathy or drug-resistant focal epilepsy." (PMID 41437099, 2025). "SLC35A2‐CDG is associated with early‐onset epileptic encephalopathies (EOEEs)." (PMID 40191061, 2025). "De novo variants in this gene are associated with SLC35A2-CDG, often with epileptic encephalopathy as a prominent feature." (PMID 41437099, 2025).
focal epilepsy (6 papers, 2019 to 2025). A seizure caused by a localized disorder. "In recent years, somatic mutations in SLC35A2, which encodes an enzyme involved in glycosylation, have been found in focal epilepsy specimens and seem to be specific to FCD type I137,145,146." (PMID 32895508, 2020). "More recent reviews and series have strengthened the evidence that somatic SLC35A2 mutations are not only recurrent but among the most frequent genetic alterations identified in otherwise non-lesional or subtly lesional focal epilepsies undergoing surgical evaluation." (PMID 41373710, 2025). "SLC35A2 encodes a uridine diphosphate–galactose transporter recently involved in a subset of non-lesional intractable focal epilepsies and mild MCDs, as well as to X-linked dominant early infantile epileptic encephalopathy-22 (MIM #300896) when the variants are germline." (PMID 31444548, 2019). "Interestingly, it has been recently reported that somatic variants in SLC35A2 in human brain tissues are associated with nonlesional focal epilepsy or mild malformation of cortical development." (PMID 31231989, 2019).
colorectal cancer (3 papers, 2017 to 2025). A primary or metastatic malignant neoplasm that affects the colon or rectum. "Association between SLC35A2 expression and clinicopathological characteristics of colorectal cancer patients (n = 60)." (PMID 37889544, 2023). "We discovered that SLC35A2 enhances MYC expression in CRC, and since MYC is a crucial transcription factor promoting colorectal cancer progression 2, this suggests a potential role for SLC35A2 in cancer development." (PMID 40303483, 2025). "We verified by IHC, WB and PCR that the expression of SLC35A2 was up-regulated in colorectal cancer tissues and cell lines, and its high expression was related to the tumor pathological stage of CRC clinical samples." (PMID 37889544, 2023). "The results showed that in colorectal cancer, the expression of SLC35A2 was positively correlated with the expression of four MYC-associated genes, including MYC, Cyclin dependent kinase 4 (CDK4), Polo like kinase 1 (PLK1), and Pescadillo ribosomal biogenesis factor 1 (PES1)." (PMID 40303483, 2025). "In summary, as an oncogene, SLC35A2 is highly expressed in colorectal cancer tissues and cells." (PMID 37889544, 2023). "Thus, high SLC35A2 levels in microsatellite stable (MSS) tumors might be responsible for the failure of immunotherapy in colorectal cancers." (PMID 40303483, 2025). "To further understand the potential biological pathways involving SLC35A2 in colorectal cancer, we utilized gene set enrichment analysis (GSEA) and explored the relationship between SLC35A2 expression and drug sensitivity by analyzing data from Cancer Cell Line Encyclopedia (CCLE) and TCGA." (PMID 40303483, 2025). "Nevertheless, the role of SLC35A2 is not yet clearly identified in colorectal cancer." (PMID 40303483, 2025). "Therefore, targeting SLC35A2 and MYC may be effective approaches for treating colorectal cancer." (PMID 40303483, 2025).
developmental delay (3 papers, 2018 to 2025). "We identified a de novo splice site variant in SLC35A2 (NM_005660.2: c.274+1G>A) in a female patient who showed severe developmental delay, spastic paraplegia, mild cerebral atrophy, and delayed myelination on MRI, but no seizures." (PMID 31231989, 2019). "Here, we present a patient with a splice site variant (c.274+1G>A) in SLC35A2 showing severe developmental delay, spasticity, and delayed myelination of white matter." (PMID 31231989, 2019). "In this report we describe a female child with growth retardation, hypotonia and global developmental delay who was found by whole exome sequencing (WES) to be mosaic for an SLC35A2 mutation previously reported." (PMID 29907092, 2018). "A 27 month old girl with developmental delay, central hypotonia, cerebral atrophy, and failure to thrive with growth retardation was identified by whole exome sequencing to have a mosaic missense variant in SLC35A2 (c.991G > A)." (PMID 29907092, 2018).
growth deficiency (3 papers, 2023 to 2025). "While SLC35A2-CDG typically shows a strong gender bias, with most cases occurring in females, there have been reports of male patients with a milder phenotype, including minor neurological involvement and growth deficiency." (PMID 41437099, 2025).
hepatocellular carcinoma (3 papers, 2021 to 2025). A malignant tumor that arises from hepatocytes. "In addition, a gene set enrichment analysis (GSEA) indicated that SLC35A2 is a key E2F target, a transcription factor involved in several types of cancer, including pancreatic adenocarcinoma and hepatocellular carcinoma, as well as expressing the immune-related impact on ER+/HER2− BRCA." (PMID 34944621, 2021).
infantile spasms (3 papers, 2019 to 2025). A rare epilepsy syndrome characterized by onset of epileptic spasms in infants between 2 and 12 months of age, and rarely up to 24 months. "The genetic landscape of infantile epileptic spasms syndrome due to focal malformations comprises germline and somatic variants in a range of genes, with mTORopathies and SLC35A2-related mild malformation of cortical development with oligodendroglial hyperplasia being the major causes." (PMID 39926610, 2025). "A higher occurrence of infantile spasms was observed in patients with SLC35A2 somatic variants (4/4 subjects) compared to panel-negative FCD1/mMCD cases (3/14, p = 0.011)." (PMID 31444548, 2019). "The only feature distinguishing SLC35A2 cases from panel-negative cases was a higher proportion of infantile spasms in SLC35A2-MOGHE cases (77% vs. 36%, p = 0.01)." (PMID 33407896, 2021).